POFUT4 (protein O-fucosyltransferase 4)
Description:
Protein O-fucosyltransferase that specifically catalyzes O-fucosylation of serine or threonine residues in EMI domains of target proteins, such as MMRN1, MMRN2 and EMID1. Attaches fucose through an O-glycosidic linkage. O-fucosylation of EMI domain-containing proteins may be required for facilitating protein folding and secretion. Also shows minor alpha-(1,3)-fucosyltransferase activity toward activity toward biantennary N-glycan acceptors. However, this was tested with a library of synthetic substrates and this activity is unsure in vivo.
Synonyms: FUT11; MGC33202; FUCTXI
Tractability: Antibody: UniProt predicts a signal peptide or a membrane-spanning region. PROTAC: ubiquitination databases record sites on it; its protein half-life has been measured.
Gene: Protein-coding gene on chromosome 10 (73,772,276 to 73,780,251, forward strand). Ensembl gene ENSG00000196968.
Subcellular location: Endoplasmic reticulum membrane
Subcellular location (Human Protein Atlas): Nuclear membrane; Golgi apparatus
Pathways (Reactome):
Metabolism of proteins: O-linked glycosylation
Gene Ontology:
Molecular function: fucosyltransferase activity; peptide-O-fucosyltransferase activity; protein binding; alpha-(1->3)-fucosyltransferase activity
Biological process: positive regulation of protein secretion; protein O-linked glycosylation; glycoprotein biosynthetic process; N-glycan processing
Cellular component: endoplasmic reticulum; endoplasmic reticulum membrane; Golgi membrane; membrane
Genetic constraint (gnomAD): Loss-of-function variants: 39 observed, 36.09 expected, observed/expected ratio (o/e) 1.08, 90% interval 0.84 to 1.41. The synonymous counts are far from expectation, so gnomAD's model fits this gene poorly and the ratio says little. Missense variants: 758 observed, 664.01 expected, observed/expected ratio (o/e) 1.14, 90% interval 1.08 to 1.21. Synonymous variants: 354 observed, 289.77 expected, observed/expected ratio (o/e) 1.22, 90% interval 1.12 to 1.33.
Homologues: Orthologues: chimpanzee FUT11 (99% identical), macaque FUT11 (97% identical), dog FUT11 (89% identical), pig FUT11 (89% identical), rabbit FUT11 (89% identical), rat Fut11 (88% identical), guinea pig FUT11 (86% identical), mouse Fut11 (86% identical), tropical clawed frog fut11 (59% identical), zebrafish fut11 (53% identical), Caenorhabditis elegans fut-1 (16% identical), Caenorhabditis elegans fut-3 (16% identical), and 11 more. Paralogues in human: POFUT3 (37% identical), FUT4 (18% identical), FUT3 (18% identical), FUT6 (18% identical), FUT5 (17% identical), FUT9 (17% identical), FUT7 (16% identical).
Diseases named in the same sentence as POFUT4 in open-access papers:
POFUT4 is named in the same sentence as 27 diseases in open-access papers, as found by Europe PMC text mining. Sharing a sentence is not in itself a finding about the gene and the disease. The quoted sentences say what the papers report.
gastric cancer (3 papers, 2024 to 2025). A primary or metastatic malignant neoplasm involving the stomach. "Elevated expression of POFUT4 in gastric cancer is linked to poor survival and may serve as a promising biomarker for cancer." (PMID 39775168, 2025). "Elevated expression of POFUT4 was observed in gastric cancer (GC) tissues compared to non-tumor adjacent tissues and is correlated with poor prognosis and survival in GC patients." (PMID 40286076, 2025).
hepatocellular carcinoma (2 papers, 2024 to 2025). A malignant tumor that arises from hepatocytes. "Overexpression of POFUT4 and its correlation with poor prognosis were also reported in multiple other cancer types, including clear cell renal cell carcinoma (ccRCC), colon adenocarcinoma (COAD), hepatocellular carcinoma (HCC), and pancreatic cancer (PC)." (PMID 40286076, 2025).
cancer (7 papers, 2014 to 2025). A tumor composed of atypical neoplastic, often pleomorphic cells that invade other tissues. "Although the related protein substrates and mechanisms underlying POFUT4’s role in cancer development and progression remain unknown, these findings suggest that targeting POFUT4 holds therapeutic potential and may serve as a novel biomarker for cancer prognosis." (PMID 40286076, 2025). "However, aberrant expression of POFUT4 has been associated with several types of cancer." (PMID 40286076, 2025).
POFUT4 also shares sentences with these, for which no sentence is quoted: tumor (5 papers); breast carcinoma (3); clear cell renal cell carcinoma (2); asthma (1); autosomal dominant polycystic kidney disease (1); colon adenocarcinoma (1); cystic fibrosis (1); diabetes (1); endometrial carcinoma (1); endometriosis (1); glioma (1); gynecological cancers (1); invasive ductal carcinoma (1); Kidney (1); melanoma (1); non-small cell lung carcinoma (1); osteosarcoma (1); pancreatic cancer (1); renal cell carcinoma (1); Sepsis (1); staphylococcus aureus infection (1); stomach adenocarcinoma (1); Thyroid carcinoma (1); virus infection (1).